CD4 (CD4 molecule)
Diseases named in the same sentence as CD4 in open-access papers (continued):
Sharing a sentence is not in itself a finding about the gene and the disease.
tumor (continued). "In addition, while most immunotherapies focus upon cytotoxic CD8+ populations, the role of CD4+ Th1 cytotoxic and helper functions is increasingly recognized as necessary to drive anti-tumor immunity." (PMID 35406595, 2022). "Overall, the expression of ANLN was found to be associated with the infiltration levels of CD8+ T cells in 13 tumor types, CD4+ T cells in 20 tumor types, B cells in 20 tumor types, macrophages in 20 tumor types, neutrophils in 26 tumor types, and NK cells in 15 tumor types." (PMID 35568883, 2022). "Besides, B cells and CD4+ T follicular helper cells synergically promoted the anti-tumor CD8+ T cell responses." (PMID 36263174, 2022). "In transgenic mice that lack LEC-specific MHC-II expression, heterotopic tumor growth is attenuated, which is associated with increased numbers of tumor-specific CD8+ and effector CD4+ T cells, as well as decreased numbers of T regulatory CD4+ cells in the TME." (PMID 36362253, 2022). "Strong infiltration by CD4 T cells in oropharyngeal squamous cell carcinoma (OPSCC) was associated with lower T stage, improved disease specific survival and prolonged overall survival supporting a role for these cells in the anti-tumor immune response." (PMID 35937775, 2022). "In addition, we found distinct CD4+ T-cell subsets that revealed an individual pattern, potentially representing a unique response of the tumor cells to the tumor microenvironment." (PMID 35406628, 2022). "Similarly, in animal models, glucose uptake and the effective function of anti-tumor CD4+ T cells are inversely related to the glycolytic activity of tumor cells, and access to glucose in the TME increases cytokine production from anti-tumor CD8+ T cells." (PMID 36483029, 2022). "Relative to preceding timepoints, at the time of tumor progression (Week 60 timepoint), activation markers and immune checkpoints were highly expressed in Treg cells, but relatively decreased in effector cells (CD4 and CD8)." (PMID 35440655, 2022). "Anthracyclines can induce the translocation of calreticulin from the cytoplasm to cell surface in tumour cells, which leads to their recognition by dendritic cells (DCs) and tumour antigen processing and presentation to CD4+ T and CD8+ T cells, thereby stimulating the antitumour immune response." (PMID 35665592, 2022). "A total of 16 CD4+ or CD8+ tumour‐infiltrating T‐cell subclusters were identified in all samples." (PMID 36471481, 2022). "We found that bacteria-positive tumours showed reduced expression levels of CD4 and CD8, along with an increased expression of immunosuppressive molecules such as CTLA4 and ARG1, and an enrichment of CD66b+ myeloid cells, supporting previous bulk tissue analysis." (PMID 36385528, 2022). "A three-dimensional analysis of immune pattern of NAFLD-related HCC shows that a CD8+ > CD4+, Th1 > Th17 > Th2 pattern is related with tumor progression, while an equilibrium Th1 = Th17 = Th2 pattern in female and a semi-equilibrium Th1 = Th17 > Th2 pattern are associated with remission from HCC." (PMID 36457551, 2022). "The results of IHC analyses revealed that the tumor tissues derived from the “Panc 02 + rHSP90α-treated RAW264.7” grafts contained more CD163+ cells but significantly reduced levels of CD4+ T-cells when compared with the tumor masses taken from other groups of mice." (PMID 35053345, 2022). "Cytotoxic CD4+ T cells directly or indirectly eliminate MHC class II-positive tumor cells." (PMID 36316775, 2022). "The DP CD4+ TILs were highly activated in the tumor and had a distinct TCR repertoire." (PMID 35439168, 2022). "This ICD induction increases the serum levels of proinflammatory cytokines, such as TNF-α, IL-6, and IFN-γ, while also improving the tumor infiltration of CD4+ and CD8+ cells, eradicating the primary tumor, and preventing lung metastasis through an abscopal effect." (PMID 35214129, 2022). "Type 1 helper cells and CD4 T cells exert a crucial effect on the anti-tumor environment." (PMID 35264912, 2022).
tumor (continued). "Meanwhile, the expression of GPX8 was associated with the infiltration of CD8+ T cells, tumor-associated fibroblasts, plasma cells, macrophages, myeloid dendritic cells, neutrophils, and CD4+ T cells in the GBM microenvironment, but not with NK cells." (PMID 36061208, 2022). "CAFs may contribute to immune evasiveness of tumours by blocking effector T cell proliferation and promoting differentiation of CD4+CD25+ T lymphocytes into Tregs." (PMID 36476325, 2022). "After treatment with AOZN, a more marked increase in CD8- and CD4-positive T cells was observed in the tumor tissue, while there is a significant decrease in the frequencies of regulatory T cells and CD8 T cell exhaustion in the AOZN group, as compared to those in the control group." (PMID 35673561, 2022). "In addition, Tregs being fundamentally different from CD8+ T cells and CD4+ T cells can utilize lactate in the tumor microenvironment through many metabolic enzymes, although they do not require lactate to survive." (PMID 35454171, 2022). "Indeed, T cell infiltrates were evident, but the numbers per g of tumor were 46% lower for CD4+ cells and 65% lower for CD8+ cells on D7 than D14." (PMID 36531040, 2022). "Accumulating evidence has shown the ability of CD4+ T cells to eradicate tumor cells." (PMID 35885563, 2022). "However, most solid tumors do not express MHC class II molecules, which limit the ability of CD4+ T cells to act at the tumor site." (PMID 36090896, 2022). "Since the observation of a population of immunosuppressive CD4+ T-cells in sarcoma tumor-bearing mice, a steadily increasing number of studies has demonstrated an important role for Treg cells regulating anti-tumor immunity." (PMID 35874729, 2022). "The VEGFR2-targeting TKI cabozantinib was also associated with a reduction in the number of Tregs and MDSCs, and simultaneously promoted tumor infiltration of CD4+ and CD8+ T lymphocytes, both alone and in combination with the anti-cancer vaccine MVA/rF-CEA/TRICOM." (PMID 35281003, 2022). "Also, females sustained an anti-tumor CD8+ > CD4+ pattern while males shifted to a CD8+ = CD4+ pattern in the liver." (PMID 35235789, 2022). "Moreover, the percentages of NK cells, T cells (CD8+ T and CD4+ T), DCs and M1 macrophages among tumor-infiltrating lymphocytes were significantly reduced after ALKBH5 silencing, and this pattern was reversed after murine IFNα injection." (PMID 35395767, 2022). "Conversely, TGFβ/IFNγ-producing CD4 T cells are the main components of pro-tumor immune reactions." (PMID 36289759, 2022). "We showed that Treg cells could suppress the proliferation of naive CD4+ T cells and inhibit IL-2 secretion of CD4+ effector cells upon activation by tumor-specific antigens." (PMID 35309296, 2022). "The percentage and AC of Tn/Tm had severely reduced in aNSCLCs compared to NCs, and the decrease in AC was more regular, especially the AC of CD4+ Tn and CD8+ Tn was associated with the disease stage of the tumor, that is, with the disease progression of aNSCLCs." (PMID 36119064, 2022). "Moreover, a considerable association was found between COPB2 expression and the indicators of TIME, such as MHC class I (MHC I), MHC class II (MHC II), CD4+ tumor-infiltrating lymphocytes (TILs), and CD8+ TILs in our cohort." (PMID 35454945, 2022). "Furthermore, our results confirmed that most immune cells in the tumor microenvironment, including B cells, CD4+ T cells, CD8+ T cells, neutrophils, macrophages, and dendritic cells, were negatively associated with FAM72B expression in LUAD." (PMID 35707363, 2022). "CD39+CD4+ TSTs expressed a highly exhausted phenotype but simultaneously expressed a large number of activation/co-stimulation genes that resisted exhaustion to expand in vitro in response to autologous tumor antigens." (PMID 36451828, 2022). "Also, studies have shown that BCG is mainly dependent on the specific CD4 T cells, and inducing and promoting tumor elimination by increasing the interferon‐γ signaling." (PMID 35522104, 2022).
tumor (continued). "In addition, T-cell CD4 memory activated and macrophages M1 were enriched in normal tissues, whereas Tregs were increased in tumor tissues." (PMID 35875096, 2022). "Thus, HCT/130-mono-IL12 demonstrated the ability to efficiently promote tumor infiltration and activation of antitumor CD4+ and CD8+ T cells, thereby increasing the antitumor immunity in the TME." (PMID 36405748, 2022). "In summary, the GAS6/AXL signaling may promote macrophage, monocyte, and MDSC infiltration, decrease tumor abundance of mature DCs, NK CD4+ and CD8+ T-cells." (PMID 35572601, 2022). "Therefore, the ideal peptide vaccine should include multiple peptides derived from different antigens to boost CD4+ with CD8+ T cell response as well as mutated and unmutated tumor-associated peptides." (PMID 35342400, 2022). "Furthermore, the tumor draining lymph nodes (tdLN) of 4T-Trap treated mice were enriched in effector memory CD4+ T cells, thereby demonstrating showing a suppressed TGF-β pathway activity." (PMID 35577211, 2022). "Additionally, OVs induce cancer cell lysis, generating the immunogenic cell death signal (ICD) that has a main role in the activation of tumor-specific responses mediated by CD4+ helper cells, CD4+ and CD8+ cells." (PMID 35669438, 2022). "The additional analysis of less favorable E:T ratios, tumor re-challenge, and the analysis of phenotype and gene expression may uncover further differences between CD4+ and CD8+ CAR-T cells." (PMID 36298713, 2022). "In our CRC metastasis mouse model, significantly increased numbers of tumor-infiltrating CD4-positive T-cells isolated from PC metastasis were CD153-positive as compared to those from originating from liver metastasis (p = 0.031) or primary tumors (p = 0.0454)." (PMID 35844581, 2022). "It has been reported that the expression of HLA-DR molecules by tumor cells is associated with a good prognosis in cancer patients suggesting that direct recognition of tumor cells by CD4+ T cells could be beneficial." (PMID 35008422, 2022). "Notably, SCT treatment slightly decreased CD3+ cell fraction and increased IL‐4+ and IL‐10+ CD4+ T cell populations in the tumor‐infiltrating T cells." (PMID 34747157, 2022). "Immunoprofiling of these tumors showed that MSA-2+anti-D-1 combination did not affect the numbers of CD4+ T cells or tumor-associated F4/80-positive macrophages." (PMID 36333297, 2022). "We hypothesized that miR-128-3p may influence CD4+ Treg differentiation by regulating tumor cell release of the cytokine interleukin 16 (IL16)." (PMID 34968167, 2022). "Identifying key cellular interaction networks and the relevant soluble factors might lead to the development of new drug targets that could boost the function of the DP CD4+ cells and help recruit these cells from the stroma into the tumor area." (PMID 35439168, 2022). "In our study, the cluster with high infiltration of CD8+T cells, activated memory CD4+T cells, activated NK cells, follicular helper T cells, memory B cells, naive B cells, plasma cells, and M1 and M2 macrophages was named the high tumor immune cell infiltration (TICI) group." (PMID 35586567, 2022). "Moreover, the immunohistochemistry assay showed increased tumor-infiltrating CD4+ T and CD8+ T lymphocytes in NCTD-treated mice." (PMID 35409302, 2022). "Both tumor-infiltrating myeloid-derived suppressor cells (MDSCs) and Treg cells, which play an immunosuppressive role in the tumor microenvironment, showed a certain degree of decrease, accompanied by an increase in the proportion of CD4+ T cells." (PMID 36376293, 2022). "PD-1+ and ICOS+ TILs are enriched for tumor-reactive CD4+ Th cells." (PMID 35439168, 2022). "In addition, antigen-specific CD4+ T cells showing a Th1 IFNγ-producing phenotype were detected against tumor growth; this was identified recently as an additional mechanism for controlling tumor growth." (PMID 35217706, 2022).
tumor (continued). "Moreover, Depletion of CD4+ T cells and NK cells attenuated this anti-tumor effect, suggesting a key role of both cells in the anti-tumor immunity." (PMID 36532071, 2022). "However, the addition of seven ICD treatments to the last seven TMZm treatments and the first IO-VACR vaccine generated a clear tumor-antigen-specific CD4+ and CD8+ T-cell response." (PMID 36361831, 2022). "Several strategies for selecting neoantigens, suitable bacteria strains, genetic constructs, and translocation inducers to achieve tumor‐specific activations of CD4 and CD8 T‐cells are discussed in this hypothesis." (PMID 35284089, 2022). "We consequently tested the possible role that CD40–CD40L interaction might have in our in vivo model of CD4-mediated TAMs education, by giving αCD40L blocking antibody to CD4-treated tumor-bearing mice." (PMID 35903540, 2022). "The treatment with αCD25-m2a reduced the fraction of CD25-expressing cells in the CD4+ T cell compartment, decreased the percentage of CD4+FoxP3+ Tregs, and increased the Teff/Treg ratios in the blood, draining the lymph nodes and tumor." (PMID 35955841, 2022). "This is also reflected in the tumour regrowth in the CD4+ depleted animals." (PMID 35808806, 2022). "The authors suggested that further studies are required to establish the consequences of PARP blockade both in terms of overall impact on CD4+ T cell infiltration at the tumor site and of the role of different CD4+ T cell subgroups in the antitumor efficacy of PARPi." (PMID 36428727, 2022). "In addition, deletion of the MHC-II molecule I-Ab on cDC1 impaired tumor rejection, consistent with a role for antigen-specific CD4 helper T cell recognition of cDC1s." (PMID 34480145, 2022). "In addition, preclinical studies have shown that the anti-tumor long term effect of anti-CD20 treatment is both CD4+ and CD8+ T cell-dependent and requires the presence of NK cells, whose expansion correlated with better clinical outcome to RTX treatment." (PMID 36569901, 2022). "Similarly, the only IClow MSI tumor identified using PCA of CD4+ TILs was identical to one of the two identified for CD8+ TILs." (PMID 36077799, 2022). "Likewise, inverse correlation was found between the ALC and CD4+ tumor‐infiltrating T cells (ρ = −0.346, p = 0.036, n = 37)." (PMID 36051040, 2022). "To dissect whether enhanced Treg frequencies from Asm-deficient mice are responsible for the enhanced tumor growth, we depleted CD4+ T cells from tumor-bearing mice." (PMID 36426850, 2022). "Aberrant or dysregulated CD4+ T cell memory populations is suspected to contribute to multiple chronic or recurring inflammatory and immune-mediated disorders and to the progression of neoplastic disease." (PMID 36045676, 2022). "Second, Treg cells may also accumulate in tumour to mediate immunosuppression by conversion of conventional CD4 T (Tconv) cells to Treg cells." (PMID 36569832, 2022). "On the other hand, the numbers of other immune cells, such as CD4+ T cells, regulatory T (Treg) cells, and tumor-associated macrophages (TAMs), did not change significantly." (PMID 35183163, 2022). "Our results showed that ALDOA could be used as a biomarker for the tumor prognosis, and could be correlated with the infiltrating levels of macrophages, CD4+ T cells and CD8+ T cells." (PMID 35804089, 2022). "Changes in immune cell infiltration in nanomaterial-induced tumor vascular normalization include increased levels of tumor-infiltrating CD4+ and CD8+ T lymphocytes, natural killer cells and dendritic cells, decrease in myeloid-derived suppressor cells and polarization of TAMs from M2-to-M1 type." (PMID 36523993, 2022).
tumor (continued). "The epitopes of the captured antigens presented on human-leukocyte-antigen (HLA) molecules of APCs can initiate the activation and differentiation of tumor-specific CD4+ and CD8+ T cells in the draining lymph node, resulting in the expansion of effector T cells in secondary lymphoid organs." (PMID 35456701, 2022). "Early investigations have reported that Nr-CWS is with high immuno-stimulating and anti-tumor activities, and could directly stimulate macrophages, CD4+, and CD8+ T cells." (PMID 36110249, 2022). "Using multivariate Cox regression, we found a significant association between the presence of tumor-infiltrating CD4+ T cells and worse OS (RR: 3.98 [1.34–11.82], p=0.013) but not stromal CD4+ T cells." (PMID 36268020, 2022). "It is possible that CD4 TIL can directly mediate tumor cell killing." (PMID 36569934, 2022). "Another possibility by which CD4+ T cell-derived IFNγ might inhibit tumor growth is by acting directly on endothelial cells." (PMID 36159781, 2022). "The study aim was to investigate the expression of PD-1 and CD39 on CD4+ and CD8+ cells infiltrating tumor tissue compared to their counterparts in peripheral blood and explore its association with tumor characteristics, disease progression, and prognosis in females with TNBC." (PMID 35051220, 2022). "In addition, tumor immune infiltrate (CD4+ and CD8+ T cells) wasobserved in four of ten patients (Sangro etal., 2004)." (PMID 36206378, 2022). "This molecule is expressed in activated CD4+ and CD8+ T-cells, natural killer (NK) cells, B cells, tumour-associated macrophages (TAM), dendritic cells, and monocytes, interacting with the ligand present in antigen-presenting cells (APC) and tumour cells (TC)." (PMID 36140252, 2022). "Furthermore, we show that the DP CD4+ Th TILs were enriched in T cells that recognize tumor-associated antigens such as HPV16 E6 and E7 proteins in HPV-related HNSCC as well as tumor-specific neoantigens arising from nonsynonymous somatic mutations." (PMID 35439168, 2022). "In addition, approximately two-thirds of the CD39+CD4+ T cells in the tumor were Tregs, which is important information to consider before using this marker to isolate and expand cells for adoptive T cell therapy." (PMID 35439168, 2022). "Next, we examined the phenotypic status of tumor infiltrating CD4+ T cells." (PMID 35710296, 2022). "In addition, the number of CD4+ Foxp3+ T cells was reduced, while the proliferation of CD8+ and CD4+ effector T cells within the tumour was enhanced." (PMID 36298556, 2022). "Such personalized therapies could spare the potentially useful CD4 CTL that for instance are involved in tumor immunity and infectious disease, and thereby minimize possible detrimental side effects as only the damaging subset is affected." (PMID 35903098, 2022). "However, there is increasing interest in harnessing CD4+ T helper cells to potentiate sustained anti-tumour immunity." (PMID 35343573, 2022). "The level of CD4+ T helper (Th) 1 cells in cryo-thermal treated mice was higher while the percentage of Tregs much lower than that in the control group (naive mice received tumor rechallenge)." (PMID 35874660, 2022). "DP CD4+ Th TILs are found in proximity to MHC class II+ cells in the tumor stroma." (PMID 35439168, 2022). "In addition, many studies have been proved that activated memory CD4 T cells were a key tool for tumor healing." (PMID 35481240, 2022). "Thus, tumor-infiltrating T-cells, particularly CD4+ and CD8+ T cells are important predictors of ovarian cancer." (PMID 35557956, 2022). "Thus, it is likely that DRD3 signalling on CD4+ T-cells also potentiates the anti-tumour immune response." (PMID 36428964, 2022). "Therefore, the TIMER platform was used to explore the correlation between independent prognostic biomarkers of CCGs and five type of tumor infiltration immune cells, including CD4+ T cells, CD8+T cells, B cells, neutrophils, and macrophages." (PMID 36118525, 2022).